OTOF (otoferlin)
Diseases named in the same sentence as OTOF in open-access papers (continued):
Sharing a sentence is not in itself a finding about the gene and the disease.
auditory neuropathy (continued). "In our cohort, all patients with bi-allelic OTOF mutations presented phenotypes compatible with auditory neuropathy of autosomal recessive inheritance." (PMID 31581539, 2019). "Genes underlying two common forms of auditory neuropathy are OTOF resulting in synaptopathy and OPA1 resulting in neuropathy of the spiral ganglion dendrites." (PMID 28174524, 2017). "OTOF mutations are common in patients with auditory neuropathy, which is characterized by normal outer hair cell function and abnormal neural conduction." (PMID 24164807, 2013). "The aim of this study is to identify OTOF mutations in Chinese patients with non-syndromic auditory neuropathy." (PMID 20504331, 2010). "We also detected one case each (2.5% of total abnormalities) of Wilson’s disease (mutations in ATP7B), cystic fibrosis (mutations in CFTR), Cockayne syndrome (mutations in ERCC6), auditory neuropathy (mutations in OTOF), and autosomal recessive polycystic kidney disease (mutations in PKHD1)." (PMID 41329681, 2025). "OTOF mutations are the principal causes of auditory neuropathy." (PMID 38014592, 2024). "Additionally, 2/26 patients were carriers of biallelic variants in OTOF, which is associated with auditory neuropathy, autosomal recessive 1 (MIM: # 601071)." (PMID 36979683, 2023). "Interestingly, there is a clinically isolated mutation linked to auditory neuropathy at the conserved Pro residue in otoferlin (P1987R) that likely disrupts the hydrophobic packing of otoferlin’s TM span." (PMID 35901179, 2022). "We will focus on whether biallelic OTOF mutations are ideal indications for CI in patients with auditory neuropathy." (PMID 32508568, 2020). "Therefore, the site of lesion in auditory neuropathy patients with biallelic OTOF mutations (OTOF-related auditory neuropathy) is presumed to be presynaptic, and auditory nerve function is assumed to be intact." (PMID 32508568, 2020). "Auditory neuropathy with biallelic OTOF mutations is an ideal surgical indication for CI." (PMID 32508568, 2020). "Reported causes of presynaptic auditory neuropathy include perinatal hypoxia, OTOF mutations, and mitochondrial mutations, while reported causes of postsynaptic auditory neuropathy include prematurity, kernicterus, autosomal dominant optic atrophy, Pelizaeus-Merzbacher disease, and CND14,19." (PMID 32555439, 2020). "For instance, previous studies reported that patients with auditory neuropathy with OTOF mutations usually had excellent CI outcomes, likely because the pathology is confined to the synapse, and postsynaptic neurons and nerve fibers are intact for electrical stimulation of CI46–48." (PMID 32555439, 2020). "The main goal is to confirm whether biallelic OTOF mutations are ideal indications for CI in patients with auditory neuropathy." (PMID 32508568, 2020). "Excluding the 48, 3 and 11 patients who were confirmed to have acquired, syndromic auditory neuropathy, and CND-related auditory neuropathy, respectively, recessive OTOF mutations accounted for 12 (30.8%) of the remaining 39 patients with non-syndromic non-acquired auditory neuropathy." (PMID 32555439, 2020). "Auditory neuropathy was associated with one novel variant in the OTOF gene." (PMID 31850270, 2019). "Similarly, humans with auditory neuropathy due to mutations in otoferlin, a protein essential for synaptic transmission between hair cells and cochlear neurons, show a robust SP and a minimal AP." (PMID 27618300, 2016). "Notably, individual R5, who had been prescreened for mutations in OTOF because of suspected auditory neuropathy, was homozygous for the classic c.35delG mutation in GJB2." (PMID 24875298, 2014). "MYO3 A, OTOF, and USH1 C are all associated with HC pathology, while OPA1 is associated with auditory neuropathy." (PMID 40268851, 2025). "We focused on DFNB9 auditory neuropathy (MIM 601071), which results from mutations of OTOF which encodes otoferlin, a calcium sensor for synaptic exocytosis in inner hair cells of the inner ear." (PMID 38952419, 2024).
auditory neuropathy (continued). "Genetic causes of non-syndromic auditory neuropathy include autosomal dominant mutations in DIAPH3 and PCDH9; autosomal recessive mutations in OTOF, PJVK, and GJB2; and mitochondrial mutations in MT-RNR19,11." (PMID 32555439, 2020). "Among these genetic defects, mutations in OTOF gene (MIM# 603681) were the first identified and the most common cause of congenital auditory neuropathy." (PMID 32508568, 2020). "OTOF mutations are another common cause of childhood SNHI, and the leading genetic cause of auditory neuropathy in Taiwanese patients, as in other populations." (PMID 31581539, 2019). "Unlike other types of auditory neuropathy, the CI performances of the patients with biallelic OTOF mutations are predictable and comparable to those of “typical” SNHL." (PMID 32508568, 2020). "Based on the finding that OTOF variants disrupt presynaptic function in IHCs rather than neuronal function, a change in terminology from “auditory neuropathy” to “auditory synaptopathy” has been adopted to more precisely describe this." (PMID 33256196, 2020). "Nineteen patients underwent cochlear implantation, including 11 patients with genetic causes (9 patients with OTOF mutations, 1 with Wolfram syndrome, and 1 with autosomal dominant optic atrophy), 2 patients with CND, and 6 patients with indefinite auditory neuropathy." (PMID 32555439, 2020). "The OTOF gene (Locus: DFNB9), encoding otoferlin, is reported to be one of the major causes of non-syndromic recessive sensorineural hearing loss, and is also reported to be the most common cause of non-syndromic recessive auditory neuropathy spectrum disorder (ANSD)." (PMID 31095577, 2019). "Finally, sequencing of OTOF in the auditory neuropathy spectrum disorder (ANSD) led to molecular genetic diagnosis only in one of five CI cases with ANSD, calling the usefulness of this approach for ANSD into question at least for CI candidates/implantees in this population." (PMID 25373420, 2014).
autosomal recessive deafness (11 papers, 2013 to 2025). "Mutations in the otoferlin gene have been linked to sensorineural hearing loss (auditory neuropathy autosomal recessive 1) and non-syndromic sensorineural hearing (Autosomal recessive deafness 9) loss in humans." (PMID 35901179, 2022). "However, some studies from the United States, Belgium, Northern Europe, and East Asia indicated that pathogenic variants in SLC26A4, MYO15A, OTOF, and CDH23 are probably the most common causes of autosomal recessive hearing loss, after the exclusion of variants in the DFNB1 locus." (PMID 39498320, 2024). "Although some reports have described OTOF mutations in severe to profound autosomal recessive hearing loss patients in other populations, there has been no literature available regarding the screening of OTOF mutations using a large cohort in a comprehensive manner." (PMID 24053799, 2013).
nonsyndromic deafness (5 papers, 2012 to 2025). An auditory system disease that is associated with permanent hearing loss caused by damage to structures in the inner ear and/or the middle ear, which is not associated with other signs and symptoms. "Mutations in FER1L2 (otoferlin) result in non-syndromic deafness (DFNB9), due to the failure of synaptic vesicles to fuse and exocytose their cargo at the presynaptic plasma membrane." (PMID 22761893, 2012). "Importantly, AlphaFold predictions support the presence of a similarly organized Fercore in all remaining paralogs, including otoferlin, whose mutations cause the nonsyndromic deafness DFNB9 and are a target of the first inner ear gene-therapy trials." (PMID 40437073, 2025). "Mutations in OTOF (otoferlin) can be the cause of nonsyndromic deafness DFNB9." (PMID 32106631, 2020).
sensorineural hearing loss (5 papers, 2019 to 2024). "We found, through the official clinicaltrials.gov register, three clinical studies currently testing AAV gene therapies in humans, specifically in patients diagnosed with sensorineural hearing loss caused by biallelic OTOF mutations." (PMID 38525683, 2024). "In conclusion, genes distribution of AN, with the most common genes being OTOF and AIFM1, is totally different from other sensorineural hearing loss." (PMID 38456936, 2024). "The OTOF gene (Locus: DFNB9), encoding otoferlin, is reported to be one of the frequent causes of non-syndromic recessive sensorineural hearing loss." (PMID 31095577, 2019).
bladder urothelial carcinoma (2 papers, 2019 to 2023). "In three cancers, we found a significant impact of otoferlin expression on survival: in renal clear cell, papillary cell carcinoma, and in bladder urothelial carcinoma." (PMID 37538852, 2023). "Although ferlins importance in cancer has not been extensively studied, data show that otoferlin expression is significantly associated with survival in specific cancer types, including clear cell and papillary cell renal carcinoma, and urothelial bladder cancer." (PMID 37538852, 2023).
COVID-19 (2 papers, 2023 to 2024). A disease caused by infection with severe acute respiratory syndrome coronavirus 2. "For PC2, the most contributing genes were IFI27, involved in type I interferon cell response, and OTOF, both over-expressed in COVID-19 patients and associating with the severity of evolution." (PMID 38772950, 2024).
muscular dystrophy (2 papers, 2007 to 2020). Muscular dystrophy (MD) refers to a group of more than 30 genetic diseases characterized by progressive weakness and degeneration of the skeletal muscles that control movement. "Mammals have several ferlin genes and mutations in the human dysferlin (DYSF) and otoferlin (OTOF) genes result in muscular dystrophy and hearing loss, respectively." (PMID 17386097, 2007).
neuropathy (2 papers, 2021). A disorder affecting the nervous system that manifests with pain, tingling, numbness, and/or muscle weakness. "Both the UNC13A and OTOF genes are associated with neuropathy." (PMID 34828297, 2021).
Usher syndrome type 1 (2 papers, 2014 to 2023). A syndrome characterized by congenital, bilateral, severe sensorineural hearing loss, abnormalities in the vestibular system, and adolescent-onset retinitis pigmentosa. "In particular, from the prognostic perspective, we can expect successful results of CI in hereditary deafness with mutation of specific genes, such as, GJB2, SLC26A4, mitochondrial mutations, OTOF, Usher syndrome type I, DFNA9 (COCH), and DFNA17 (MYH9)." (PMID 25373420, 2014). "In addition to MYO7A (DFNA11, DFNB2, and Usher syndrome type I), OTOF (DFNB9), CDH23 (DFNB12 and Usher syndrome type I), and WHRN (DFNB31) are present within the hair cell or its stereocilia." (PMID 37289589, 2023).
clear renal cell carcinoma (1 paper, 2022). "Additionally, an increased Otoferlin transcript level correlates with poor prognosis in clear renal cell carcinoma." (PMID 35330493, 2022).
glaucoma (1 paper, 2021). Increased pressure in the eyeball due to obstruction of the outflow of aqueous humor. "In particular, the otoferlin gene (OTOF) exhibited the riskiest to glaucoma with OR = 9.727, and it also showed remarkable ability in discriminating the glaucoma-inducing drugs from the non-glaucoma-inducing drugs with an AUC = 0.755." (PMID 33874942, 2021).
HIV-1 infection (1 paper, 2022). The type species of lentivirus and the etiologic agent of acquired immunodeficiency syndrome (AIDS). "In contrast, OTOF transcript levels were similar between ART-treated patients and healthy donors, indicating that OTOF upregulation is due to the spread of HIV-1 infection in vivo." (PMID 35862790, 2022). "The inhibitory effect of IFN-α on HIV-1 infection dropped from 16.5- to 8-fold when OTOF was depleted." (PMID 35862790, 2022). "The ectopic expression of OTOF resulted in significant inhibition of HIV-1 infection." (PMID 35862790, 2022). "Furthermore, silencing OTOF partially relieved IFN-α-induced resistance to HIV-1 infection in macrophages or DCs." (PMID 35862790, 2022). "Therefore, OTOF is likely a membrane protein that protects target cells from HIV-1 infection." (PMID 35862790, 2022). "Thus, we hypothesized that this upregulation of OTOF expression might be because of IFN-α stimulation in vivo due to HIV-1 infection." (PMID 35862790, 2022). "In the presence of OTOF, IFN-α treatment reduced HIV-1 infection by 13.1-fold; however, silencing OTOF reduced the IFN-α-mediated suppression by 2.73-fold, indicating that OTOF contributes to IFN-α-mediated resistance to HIV-1 infection in primary macrophages." (PMID 35862790, 2022). "Ca2+ did not affect the inhibitory effect of OTOF on HIV-1 infection compared with Mg2+, implying that the antiviral function of OTOF is not dependent on Ca2+." (PMID 35862790, 2022). "To investigate whether IFN-α induces OTOF to suppress HIV-1 infection in myeloid cells, we silenced OTOF in stimulated THP-1 cells using RNAi with or without IFN-α treatment." (PMID 35862790, 2022). "To further investigate the molecular mechanisms through which OTOF inhibits HIV-1 infection, we infected 293T cells with an HIV-1NL4-3.Luc.R−.E− reporter virus at different doses in the presence or absence of overexpressed OTOF protein." (PMID 35862790, 2022).
influenza (1 paper, 2025). An acute viral infection of the respiratory tract, occurring in isolated cases, in epidemics, or in pandemics; it is caused by serologically different strains of viruses (influenzaviruses) designated A, B, and C, has a 3-day incubation period, and usually lasts for 3 to 10 days. "Our study found that IFI27 and OTOF protein levels were significantly reduced in children with influenza." (PMID 40718794, 2025). "The results of in-depth verification indicated that the hub genes IFI27 and OTOF found in children’s influenza were accurate." (PMID 40718794, 2025).
oral squamous cell carcinomas (1 paper, 2022). "Our study describes the neoexpression (Juno) and suppression (catsperD, dysferlin, Fer1L5 and otoferlin) of selected genes in oral squamous cell carcinomas (OSCCs)." (PMID 35330493, 2022).
Sepsis (1 paper, 2025). Sepsis is defined as life-threatening organ dysfunction caused by a dysregulated host response to infection. "Within the GSE42026 validation set, there was a significant difference (P < 0.01) in the expression of IFI27 and OTOF between the pediatric sepsis and control groups." (PMID 40718794, 2025).
Vertigo (1 paper, 2019). An abnormal sensation of spinning while the body is actually stationary. "In this study, we also investigated whether the patients with biallelic OTOF mutations experience episodes of vertigo, and found that 31 of 32 patients (96.9%) with biallelic OTOF mutations had no such episodes." (PMID 31095577, 2019). "Clinical information regarding vertigo was available for 32 of the 39 patients with biallelic OTOF mutations, with 31 of them (96.9%) not experiencing any episodes of vertigo." (PMID 31095577, 2019).
virus infection (1 paper, 2016). "Down-regulation of transporter related genes, such as lactase-phlorizin hydrolase (LPH), B(0,+)-type amino acid transporter 1 (BAT1), actin cytoskeleton-regulatory complex protein PAN1 (PAN1), MFS-type transporter (MFS), and otoferlin, could repress virus infection in host cells." (PMID 27168061, 2016).
genetic disorders (4 papers, 2010 to 2023). "There are six mammalian ferlins (Fer1L1-6), with mutations in FER1L1 (dysferlin) and FER1L2 (otoferlin) linked to inherited diseases in humans." (PMID 20667140, 2010).
cancer (3 papers, 2015 to 2023). A tumor composed of atypical neoplastic, often pleomorphic cells that invade other tissues. "Interestingly, otoferlin expression was either a protective or a risk factor depending on the histology of the cancer." (PMID 37538852, 2023). "Intriguingly, beyond a simple alteration, myoferlin, otoferlin and Fer1L4 expressions were negatively correlated with patient survival in some cancer types." (PMID 31443490, 2019).
infection (2 papers, 2022 to 2023). The state of being infected such as from the introduction of a foreign agent such as serum, vaccine, antigenic substance or organism. "Many antiviral ISGs were upregulated in early stages of infection, with IFI27, OTOF, ISG15, MX1 and USP18 the most highly overexpressed." (PMID 37077524, 2023). "Interestingly, the ectopic expression of OTOF significantly suppressed only HIV-2 infection and exerted a mild effect on SIV infection but had no evident effect on EIAV or MLV infection in target cells." (PMID 35862790, 2022).
tumor (2 papers, 2022 to 2023). "As a result of this approach, particularly Juno as a real tumor marker but also four additional genes, namely CatsperD, Dysferlin, Fer1L5, and Otoferlin remain to be useful in characterizing oral malignancies." (PMID 35330493, 2022). "Taken together, these results suggest a role for otoferlin in the carcinogenesis of these tumors, which deserves investigation to confirm and understand its exact role, especially as it appears to vary according to tumor site." (PMID 37538852, 2023).
neurological diseases (1 paper, 2021). "Both classes of neurological diseases involved in the UNC13A and OTOF genes are reversible in clinical presentation, and the methylation levels of UNC13A and OTOF both had variability in the controlled trial of ω-3 fatty acids supplementations." (PMID 34828297, 2021).
OTOF also shares sentences with these, for which no sentence is quoted: Hearing impairment (16 papers); autosomal recessive hearing loss (2); cystic fibrosis (2); albinism (1); amyotrophic lateral sclerosis (1); autosomal dominant optic atrophy (1); autosomal recessive polycystic kidney disease (1); Cockayne syndrome (1); dermatomyositis (1); dysferlinopathies (1); Limb-Girdle Muscular Dystrophy type-2B (1); Lissencephaly (1); lupus (1); metastatic tumors (1); Mitochondrial myopathy (1); Miyoshi myopathy (1); neurodegenerative disease (1); Nystagmus (1); of hearing (1); pancreatic adenocarcinoma (1); papillary cell renal carcinoma (1); Parkinson disease (1); Pelizaeus-Merzbacher disease (1); periodontitis (1); Usher syndrome type 3A (1); Wilson disease (1); Wolfram syndrome (1).